CDH3 (cadherin 3)
Diseases named in the same sentence as CDH3 in open-access papers (continued):
Sharing a sentence is not in itself a finding about the gene and the disease.
glioma (4 papers, 2022 to 2025). A benign or malignant brain and spinal cord tumor that arises from glial cells (astrocytes, oligodendrocytes, ependymal cells). "Aberrant CDH3 expression is associated with an aggressive phenotype in various tumors, including gliomas, where its elevated levels correlate with a poor prognosis, likely due to its regulation of glial cell viability, invasion, migration, and stemness." (PMID 41304780, 2025). "In contrast, IDH‐mutant and 1p/19q co‐deleted gliomas, classically classified as oligodendroglioma, presented consistently low levels of CDH3 expression, with only 1.2% and 4.2% of grade II and III cases overexpressing CDH3." (PMID 34919784, 2022). "Focusing on each WHO malignancy grade, independently of IDH mutation and 1p/19q codeletion status, the frequency of CDH3 overexpression increased with higher tumor grades (8.5% in grade II, 15.0% in grade III, and 21.3% in grade IV gliomas)." (PMID 34919784, 2022). "To study the expression pattern of CDH3 in gliomas, we firstly analyzed its expression levels in patient samples (WHO grades II to IV) deposited in TCGA database with available RNA‐seq data." (PMID 34919784, 2022). "A wide spectrum of expression of CDH3 was observed in each glioma subgroup, reflecting the remarkable inter‐individual heterogeneity typical of glioma." (PMID 34919784, 2022). "Concordantly, CDH3 mRNA levels in glioma samples from The Cancer Genome Atlas (TCGA) database are increased in high‐grade gliomas." (PMID 34919784, 2022). "CDH3/P‐cadherin mRNA and protein levels were evaluated in human glioma samples." (PMID 34919784, 2022). "Globally, the increased percentage of CDH3/P‐cadherin overexpressing samples in grade IV gliomas suggests this molecule may be relevant for tumor aggressiveness." (PMID 34919784, 2022).
adenomyosis (3 papers, 2020 to 2025). The growth of endometrial tissue inside the muscular wall of the uterine corpus. "As a key molecule in cell-cell adhesion and EMT, cadherin 3 (CDH3) mRNA was significantly increased in adenomyosis patients." (PMID 32719721, 2020). "Possible target genes, including cadherin 3(CDH3), sodium channelβ-subunit 4 (SCN4B), and placenta-specific protein 8 (PLAC8), which are involved in cell adhesion, muscle contraction and immune response in the myometrium of adenomyosis patients were also validated." (PMID 32719721, 2020).
cyst (3 papers, 2024 to 2025). A sac-like closed membranous structure that may be empty or contain fluid or amorphous material. "Finally,we demonstrate cyst ruffling and protrusions in response to chemokinegradient and matrix architecture are dependent on Cadherin-3 (CDH3)." (PMID 39007451, 2024). "Together, these findings demonstrate RhoA rescues responsiveness of CDH3-/- cysts to HGF, enabling cyst protrusion formation, correlating to cyst morphology and matrix deformation rates similar to WT cysts." (PMID 41424915, 2025).
EEM syndrome (3 papers, 2015 to 2021). "Kjaer and colleagues first established the link between families with EEM and homozygous mutations in CDH3/P-cadherin gene in affected individuals and, up to now, three CDH3 gene mutations have been shown to lead to EEM syndrome." (PMID 26438065, 2015). "The functional importance of P-cadherin in the RPE is strongly supported by genetic case studies describing that CDH3 mutations are responsible for two rare autosomal recessive disorders: HJMD and EEM syndrome." (PMID 29338041, 2018).
glioblastoma (3 papers, 2022 to 2024). The most malignant astrocytic tumor (WHO grade IV). "Here, we identified Cadherin‐3 (CDH3) as a novel oncogene in glioblastoma (GBM)." (PMID 34919784, 2022).
liver cancer (3 papers, 2021 to 2025). An epithelial or non-epithelial malignant neoplasm that arises from the liver. "Additionally, KLF4 suppresses the growth and migration of human liver cancer cells by upregulating P-cadherin (CDH3) expression." (PMID 39995670, 2025).
diabetes (2 papers, 2017 to 2025). "In a group of the Korean population, CDH3 (cadherin-3), JAM-B, LAYN (layilin), and SCARA5 (scavenger receptor class a member 5) were also found to be positively associated with DSP in patients with diabetes." (PMID 40002826, 2025).
endometriosis (2 papers, 2014 to 2021). The growth of functional endometrial tissue in anatomic sites outside the uterine body. "In addition, some identified hub genes of the EC (TAGLN, GATA6, CDH3, CLU, COL8A1, MYH11, MYOCD) and EU (CXCL13, DDK-1, KLF4, CYP2E1, CYP4B1 and PROK1) have been reported be associated with endometriosis." (PMID 34522169, 2021).
hypotrichosis 6 (2 papers, 2022 to 2023). Any hypotrichosis in which the cause of the disease is a mutation in the DSG4 gene. "Previous studies have reported many casual genes associated with heredity hypotrichosis simplex such as LSS, CDSN, and APCDD1, while other studies highlighted that CDH3 variants cause hypotrichosis simplex with juvenile macular dystrophy (HJMD; OMIM #601553) that is manifested later in life." (PMID 35962736, 2022). "In conclusion, this is the first report highlighting a novel frameshift variant in CDH3 to be associated with heredity hypotrichosis simplex without macular degeneration based on the clinical and familial segregation data." (PMID 35962736, 2022).
Insulin resistance (2 papers, 2015 to 2019). Increased resistance towards insulin, that is, diminished effectiveness of insulin in reducing blood glucose levels. "Cadherin 3, type 1, P-cadherin (CDH3), CDH2, PCDH20, and CDH23 are novel biomarkers for the development of insulin resistance." (PMID 30678306, 2019).
kidney cancer (2 papers, 2021 to 2023). Primary or metastatic malignant neoplasm involving the kidney. "The pyrosequencing analysis of commercially available cell lines derived from human kidney cancer demonstrated a high degree of methylation in the majority of the cell lines, indicating that CDH3 CGI methylation might be a relevant event in the development of RCC." (PMID 38003666, 2023).
lung adenocarcinoma (2 papers, 2016 to 2025). A carcinoma that arises from the lung and is characterized by the presence of malignant glandular epithelial cells. "Our expression analysis revealed that CDH3, EDNRB, MAOA, and PLA2G1B matched our differential gene analysis results in IPF, Lung Adenocarcinoma (LUAD), and Lung Squamous Cell Carcinoma (LUSC) tissues." (PMID 40589973, 2025).
macular degeneration (2 papers, 2018 to 2022). Loss of vision in the central portion of the retina (macula), secondary to retinal degeneration. "This is the first report to associate CDH3 variants with a HHS phenotype without macular degeneration using WES." (PMID 35962736, 2022). "The reason why CDH3 mutations exclusively affect RPE cells in the macula is unclear, and answers to this question may also provide mechanistic insights into other macular degeneration including AMD." (PMID 29338041, 2018).
oral cancer (2 papers, 2005 to 2022). "Therefore, further study is needed to elucidate the relationship between these genes (including CDH3 and ANK3) and cancer metastasis in oral cancer cells and tissue." (PMID 35745623, 2022).
osteosarcoma (2 papers, 2018 to 2020). A usually aggressive malignant bone-forming mesenchymal neoplasm, predominantly affecting adolescents and young adults. "We also performed transcriptome analysis (RNA-seq) of flavopiridol-treated osteosarcoma cells, which revealed significant changes in genes coding for proteins involved in cell-cell and cell-matrix adhesions, including cadherin 3 (CDH3) and 4 (CDH4)." (PMID 29805751, 2018). "Thus, the increase in CDH3 expression following flavopiridol treatment may potentially suppress invasion in osteosarcoma cells." (PMID 29805751, 2018).
pancreatic ductal adenocarcinoma (2 papers, 2020 to 2024). An infiltrating adenocarcinoma that arises from the epithelial cells of the pancreas. "The top gene hit, CDH3 (Cadherin 3 or P-Cadherin), has been found to be overexpressed in a great majority of pancreatic ductal adenocarcinomas (PDACs), lending support to its key role in gastrointestinal cancers." (PMID 39484215, 2024).
papillary thyroid cancer (2 papers, 2018 to 2023). "CDH3 is associated with immune infiltration in papillary thyroid carcinoma." (PMID 36860337, 2023). "The expression of biomarkers (ITGA2, SYT12 and CDH3) was studied in a prospective cohort of patients with papillary thyroid cancer." (PMID 29255621, 2018).
prostate tumor (2 papers, 2015 to 2016). "Tissue and cell line analysis strongly suggested that the status of CDH3 in uEVs is a distal reflection of changes in the expression of this cadherin in the prostate tumor." (PMID 26771841, 2016). "We find that the decrease in abundance of CDH3 in uEVs is coherent with mRNA changes in the prostate tumor cells." (PMID 26771841, 2016). "Finally, the analysis of mRNA in prostate tumor tissue from patients revealed alterations in this gene, coherent with genomic transcriptional and epigenetic changes, all pointing at the inhibition of CDH3 in PCa." (PMID 26771841, 2016).
retinal disease (2 papers, 2010 to 2023). "We compared the significantly dysregulated genes identified in this screen (FDR <0.05) against genes linked to inherited retinal diseases and identified 5 genes: RGR, PRCD, CDH3, GM2A, and CYP2U1." (PMID 37115691, 2023). "known retinal disease genes (BEST1 [NM_004183], C1QTNF5 [NM_015645], CDH3 [NM_001793], LRAT [NM_004744], RDH5 [NM_002905], RDH11 [NM_016026], RGR [NM_002921], RLBP1 [NM_000326] and STRA6 [NM_022369])." (PMID 20479888, 2010).
sarcoma (2 papers, 2010 to 2021). A usually aggressive malignant neoplasm of the soft tissue or bone. "Aberrant expression of Cadherin 3 has been described in many carcinoma and sarcoma, including CCA." (PMID 34013637, 2021).
artery disease (1 paper, 2024). "It is important to discriminate between the role of CDH3 as a predictor of severe artery disease, thus being a predictor of revascularization and CV outcomes, and the role of CDH3 as an independent predictor of CV outcomes." (PMID 39518432, 2024).
atherosclerosis (1 paper, 2020). A disease characterized by the build-up of fatty material and calcium deposition in the arterial wall resulting in partial or complete occlusion of the arterial lumen. "TNFRSF4 is involved in atherosclerosis development and tPA is involved in thrombolysis, while PRSS8, FRalpha, MIA, FUR, CDH3 and HE4 are involved in various cancer processes." (PMID 33066363, 2020).
Atherosclerotic lesion (1 paper, 2024). A lesion associated with atherosclerosis, a multifactorial and multipart progressive disease manifested by the focal development within the arterial wall of lesions, that ranges from the development of a fatty streak, plaque progression, and plaque disruption. "Elevated serum CDH3 was the predictor of cardiovascular outcomes adjusted for age, sex, coronary atherosclerotic lesions, family history of CVD, and conventional CV risk factors and was associated with atherosclerosis predominantly in the coronary circulation." (PMID 39518432, 2024).
brain tumor (1 paper, 2022). "In this study, we investigated the functional roles, the associated molecular signatures, and the prognostic value of CDH3/P‐cadherin in this highly malignant brain tumor." (PMID 34919784, 2022). "Together, our results show that CDH3/P‐cadherin expression is associated with aggressiveness features of GBM and poor patient prognosis, suggesting that it may be a novel therapeutic target for this deadly brain tumor." (PMID 34919784, 2022).
cleft lip (1 paper, 2026). Congenital defect in the upper lip where the maxillary prominence fails to merge with the merged medial nasal prominences. "Of note, a CDH3 variant found in three unrelated individuals with cleft lip is predicted to result in premature termination c.212G>T[p.Glu708Ter] within the p120-catenin interaction domain of P-cadherin." (PMID 41231213, 2026). "Finally, we identify CDH3 variants in individuals with cleft lip, supporting the relevance of this mechanism in human tissue fusion." (PMID 41231213, 2026). "We sought to examine CDH3 and extend our understanding of the extent of involvement of actomyosin contractility and cell adhesion genes in cleft lip." (PMID 41231213, 2026).
conductive hearing loss (1 paper, 2024). "Variants in CCDC114 cause sensorineural hearing loss (SNHL), while variants in CCNO, CDH3, DNAH5 and OFD1 cause conductive hearing loss (CHL)." (PMID 38818043, 2024).
coronary stenosis (1 paper, 2024). Narrowing of the coronary artery lumen diameter. "In a previous study, we used an antibody microarray technology to demonstrate that CDH3 is one of the biomarkers that are sex-independently associated with coronary stenosis." (PMID 39518432, 2024). "Additionally, we demonstrated significant associations between CDH3 and the severity of coronary stenosis." (PMID 39518432, 2024). "Moreover, binomial regression analysis was performed to discriminate between the predicting roles of CDH3 in terms of the severity of coronary stenosis and CV outcomes." (PMID 39518432, 2024).
depression (1 paper, 2024). "Stratifying the individuals within the “depression” group by gender enabled us to identify a higher occurrence of the heterozygous variant rs3114409-A/C (p = 0.0433, n ≥ 19) in the CDH3 gene among males." (PMID 38699454, 2024). "In the “depression-male” group, we observed an increased incidence of the heterozygous variant rs3114409-A/C (p = 0.0433, n ≥ 19) in the CDH3 gene, along with a decrease in the frequency of homozygous variants." (PMID 38699454, 2024).
gastric tumours (1 paper, 2023). "CDH1 and CDH3 mRNA expression was obtained from 42 gastric tumours’ RNA-seq data." (PMID 37372088, 2023). "In 42% of gastric tumours analysed, CDH1 to CDH3 switch was observed." (PMID 37372088, 2023).
ischemia (1 paper, 2021). A hypoperfusion of the BLOOD through an organ or tissue caused by a PATHOLOGIC CONSTRICTION or obstruction of its BLOOD VESSELS, or an absence of BLOOD CIRCULATION. "Under nonischemic conditions, pericytes expressed Cdh19, Cdh6, Cdh10, Cdh4, Cdh13, and Cdh5; after ischemia, the cadherin genes that were predominantly expressed were Cdh15, Cdh11, Cdh3, and Cdh2." (PMID 33726849, 2021).
KBG syndrome (1 paper, 2023). KBG syndrome is a rare condition characterized by a typical facial dysmorphism, macrodontia of the upper central incisors, skeletal (mainly costovertebral) anomalies and developmental delay. "There are numerous monogenic neurodevelopmental disorders, including 22q11DS, Snijders Blok-Campeau syndrome (CDH3) and KBG syndrome (ANKRD11), with reports of discordant monozygotic twins and/or variable expressivity across individuals in families who inherit the same pathogenic sequence variant." (PMID 37884963, 2023).
lactic acidosis (1 paper, 2014). Metabolic acidosis characterized by the accumulation of lactate in the body. "Interestingly, by the analysis of an online available gene expression profile (E-GEOD-9649), we could observe that CDH3 gene is indeed upregulated in hypoxia compared to normoxic conditions, as well as in response to lactic acidosis." (PMID 25269858, 2014).
lymphoma (1 paper, 2023). A malignant (clonal) proliferation of B- lymphocytes or T- lymphocytes which involves the lymph nodes, bone marrow and/or extranodal sites. "Among genes of which the SNPs were associated with the clinical outcomes of this cohort of patients, some have been previously related to cancer, including lymphomas (e.g., CDH3, OXNAD1)." (PMID 37345090, 2023).
malnutrition (1 paper, 2021). Inadequate nutrition resulting from poor diet, malabsorption, or abnormal nutrient distribution. "CDH3 is a calcium-binding protein that is involved in calcium ion binding and protein binding and is associated with diseases such as malnutrition and developmental malformations." (PMID 34276758, 2021).
mental disorder (1 paper, 2024). A disease that has its basis in the disruption of mental process. "Of note, the CDH3 gene, also known as P-cadherin, hasn’t been previously associated with the pathogenesis of mental disorders." (PMID 38699454, 2024). "CDH3, or P-cadherin, although not previously implicated in the pathogenesis of mental disorders, has been shown in several studies to play a critical role in neural cell migration and nerve fiber guidance." (PMID 38699454, 2024).
metastatic cancer (1 paper, 2016). A carcinoma which has spread from the original site of growth to another anatomic site. "Interestingly, the expression of CDH3 in prostate cell lines revealed a down-regulation of the transcript in metastatic cancer cell lines (black), compared to benign-immortalized cells (grey) (0.17 ± 0.07; mean ± s.e.m.)." (PMID 26771841, 2016).
nasal polyps (1 paper, 2025). "MRNA and protein levels of PTHLH and CDH3 were notably elevated in nasal polyp tissue compared to the control group, whereas PDCD4 and AR were downregulated (P < 0.05)." (PMID 40894073, 2025). "Notably, CDH3 and PTHLH attained AUC values of 1, potentially influenced by the limited sample size of nasal polyps (NP) in the validation group (n = 27)." (PMID 40894073, 2025).
Peters anomaly (1 paper, 2025). Peters anomaly (PA) is a congenital corneal opacity disorder characterized by a central corneal leukoma that obstructs the pupil leading to visual loss as well as absence of the posterior corneal stroma and Descemet membrane. "In conjunction with CDH1 and CDH3, it controls separation of the lens vesicle from the surface ectoderm during anterior segment development; thus, its association with Peters anomaly is unsurprising." (PMID 41011222, 2025).
renal fibrosis (1 paper, 2016). A final common manifestation of a wide variety of chronic kidney diseases characterized by glomerulosclerosis and tubulointerstitial fibrosis. "The list of genes includes Fblim1, Epha2, Wisp1, Parvg, Madcam1, Mybpc2, Cdh3, Gpr56, Troap, Pstpip1, Pcdh8, Nlgn2 and Mfap4, genes that based on Pubmed and Kidney and Urinary Pathway Knowledge Base12 searches have not been previously associated with renal fibrosis." (PMID 27189340, 2016).
Retinal dystrophy (1 paper, 2017). Retinal dystrophy is an abnormality of the retina associated with a hereditary process. "As it has previously been noted the main differential diagnostic of HJMD from an ophthalmological point of view is not only Stargardt’s disease, which is caused mainly by ABCA4 mutations, but any retinal dystrophy phenotype suggestive of CDH3, regardless of the hair phenotype." (PMID 28061825, 2017).
thyroid (1 paper, 2018). "However, many other molecular profiling studies have failed to implicate the ITGA2, SYT12 and CDH3 genes in thyroid tumorigenesis." (PMID 29255621, 2018).
thyroid tumor (1 paper, 2018). A benign or malignant neoplasm affecting the thyroid gland. "In this study, we recruited a cohort of patients with PTC and determined the levels of ITGA2, SYT12 and CDH3 mRNA in resected thyroid tumors." (PMID 29255621, 2018).
urogenital cancers (1 paper, 2016). "We next ask whether the reduction of CDH3 expression observed in PCa could be extrapolated to other urogenital cancers." (PMID 26771841, 2016).
vitiligo (1 paper, 2024). Generalized well circumscribed patches of leukoderma that are generally distributed over symmetric body locations and is due to autoimmune destruction of melanocytes. "It was found that the expression of Wnt pathway components such as LEF1, CDH2, and CDH3 was downregulated in the lesional skin of vitiligo." (PMID 38361944, 2024). "In addition, it was found that the expression of Wnt pathway components such as LEF1, CDH2, and CDH3 was downregulated in the lesional skin of vitiligo." (PMID 38361944, 2024).